TGIF2 (TGFB induced factor homeobox 2)
Diseases named in the same sentence as TGIF2 in open-access papers (continued):
Sharing a sentence is not in itself a finding about the gene and the disease.
cancer (17 papers, 2012 to 2025). A tumor composed of atypical neoplastic, often pleomorphic cells that invade other tissues. "TGIF2 has been implicated in the development and progression of various cancers." (PMID 38629068, 2024). "TGFB-induced factor homeobox 2 (TGIF2), a member of the Three-Amino-acid-Loop-Extension (TALE) superfamily, has been implicated in various malignant tumors." (PMID 38629068, 2024). "Another hit in our screen, the homeobox protein TGIF2, was constitutively expressed in most tested YAPoff cancer lines, but our genetic studies suggest it is also key for YAP-mediated growth-arrest." (PMID 39172021, 2024). "TGIF2 functions in the progression of several cancer types including ovarian, gastric, prostate and colorectal cancers." (PMID 36647029, 2023). "Based on our findings, we suggest that TGIF2 can enhance the transcription of OCT4 to regulate cancer stemness." (PMID 31871777, 2019). "TGIF2 nuclear immunoreaction was seen in dysplastic epithelial cells but was repressed in cancer cells." (PMID 30333907, 2018). "Contrary to these reports, in which TGIF2 functioned as an inhibitory manner and loss of TGIF leaded to progression in cancer development, there were a few reports describing the contradictory effect of TGIF2 in cancer development." (PMID 30333907, 2018). "Further investigations are needed on some more types of cancers to reveal the TGIF2 promotive or inhibitory effect on cancer cells." (PMID 30333907, 2018). "In these reports, TGIF2 expression was lower in cancer cells than in normal cells, and these results are also consistent with our results." (PMID 30333907, 2018). "For example, miR‐148a, miR‐34b/c, and miR‐9 downregulate oncogenes, including c‐MYC, E2F3, CDK6, and TGIF2 and are often reduced in cancers." (PMID 28179359, 2017). "miR-148a-3p directly targets the cancer-related TGIF2 (TGFB-induced factor homeobox 2) and drug-metabolizing-related PXR (pregnane×receptor) genes." (PMID 22937080, 2012). "The dual role of TGIF2 in EMT may be due to differences in cancer types and microenvironments, which helps us understand the general or cancer-type-specific EMT response." (PMID 39781447, 2025). "However, few studies have investigated the mechanism by which TGIF2 is involved in cancer progression." (PMID 36647029, 2023). "Based on our and previous findings, the inhibition of EMT by targeting p-TGIF2 could also improve the outcomes in cancer immunotherapy, though this requires further validation." (PMID 36647029, 2023). "Being a target of microRNAs, TGIF2 is involved in various cancer-related processes." (PMID 36647029, 2023). "Moreover, it has been reported that TGIF2 promotes cancer cell proliferation, and the ability of Vpr to induce G2 arrest is well known." (PMID 34965271, 2021). "Additionally, TGIF2 is often involved in cancer by acting as a target of microRNAs,34–38 and few studies have investigated the mechanism of TGIF2 in cancer." (PMID 31871777, 2019). "To test whether TGIF2 regulates the stemness of LUAD cancer cells, we first examined the expression of TGIF2 in CSC-like cells." (PMID 31871777, 2019). "Importantly, silencing TGIF2 decreased the cancer stem cell (CSC)-like properties in A549 and H1299 cells." (PMID 31871777, 2019). "To further explore whether TGIF2 could drive the stemness properties in LUAD cancer cells, we established TGIF2-silenced stable H1299 and A549 cells." (PMID 31871777, 2019). "Moreover, TGIF2 has been recognized as an effective regulator in many other cancer types." (PMID 34965271, 2021). "Thus, PKM2 and its binding partner TGIF2 might be a useful clinical therapeutic target in OSCC in addition to a potential biomarker representative of the cancer cell activity or metastasis in OSCC." (PMID 30333907, 2018). "The TGIF2/SOX2 transcriptional axis contributes to EMT, cancer stem cell properties, and chemoresistance in PC and is a promising target for PC therapy." (PMID 39781447, 2025).
cancer (continued). "However, the functions of phosphorylated (p)-TGIF2 in cancer are largely unknown." (PMID 36647029, 2023). "In melanoma, TGIF2 directly upregulates the transcription of FUT8 (fucosyltransferase 8) to induce metastasis, increasing the aggressive nature of the cancer." (PMID 34965271, 2021). "In summary, we demonstrated that TGIF2 was highly expressed in LUAD and upregulated OCT4 expression downstream of EGFR/RAS/ERK signaling, promoting cancer cell stemness and metastasis of LUAD cells." (PMID 31871777, 2019). "In LUAD, we showed here that EGF-induced phosphorylation of TGIF2 promoted OCT4 transcription and enhanced the stemness of cancer cells." (PMID 31871777, 2019). "RNA-Seq data from several other YAPoff cell lines demonstrated that TGIF2 is also not YAP-induced in these cancers." (PMID 39172021, 2024). "TGIF2 is a TGF-β signaling transcriptional repressor, and the complex between PKM2 and TGIF2 promotes histone H3K9 deacetylation, resulting in a decrease in E-cadherin transcription, which contributes to metastasis by inducing EMT of cancer cells." (PMID 36115986, 2022). "Furthermore, it is also known to interact with TGF-β-induced factor homeobox 2 (TGIF2) and repress E-cadherin expression during EMT, which plays a critical role in the transition of cancer cells to the mesenchymal phenotype." (PMID 34966685, 2021).
infection (1 paper, 2023). The state of being infected such as from the introduction of a foreign agent such as serum, vaccine, antigenic substance or organism. "Among critical inflammation and immune response biomarkers, HSP100, TNF-α, TGIF-1, TGIF-2, mCCL22, iNOS, caspase-1, and caspase-8 were significant at different time points in the infection-derived EVs during CCoV infection of CRFK cells." (PMID 36979955, 2023).
TGIF2 also shares sentences with these, for which no sentence is quoted: hepatocellular carcinoma (4 papers); oral squamous cell carcinoma (2); Alzheimer disease (1); Andersen-Tawil syndrome (1); cholangiocarcinoma (1); chondrosarcoma (1); chronic obstructive pulmonary disease (1); developmental delay (1); esophageal cancer (1); esophageal squamous cell carcinoma (1); heart failure (1); Leber congenital amaurosis (1); low grade glioma (1); oral submucous fibrosis (1); osteosarcoma (1); Pancreatic Cancer (1); primary biliary cholangitis (1); prostate tumor (1); short QT syndrome (1); squamous cell carcinoma (1); type 1 diabetes (1); urethral carcinoma (1).